Y_RNA (Y RNA )
Gene: Miscellaneous RNA gene on chromosome 12 (88,430,442 to 88,430,550, forward strand). Ensembl gene ENSG00000199245.
Homologues: Orthologues: chimpanzee Y_RNA (96% identical), macaque Y_RNA (96% identical). Paralogues in human: RNY1P5 (84% identical), Y_RNA (83% identical), Y_RNA (82% identical), Y_RNA (81% identical), Y_RNA (80% identical), Y_RNA (79% identical), RNY1 (78% identical), Y_RNA (78% identical), Y_RNA (77% identical), RNY1P1 (76% identical), Y_RNA (76% identical), RNY1P11 (75% identical), and 92 more.